ABCG2 (ATP binding cassette subfamily G member 2 (JR blood group))
Diseases named in the same sentence as ABCG2 in open-access papers (continued):
Sharing a sentence is not in itself a finding about the gene and the disease.
cancer (continued). "The data on the ABCG2 sorted population can be explained by the hierarchical cancer model if we assume that ABCG2+ and ABCG2− data are distinguished by a different initial fractions of CSCs." (PMID 22275856, 2012). "One of the important issues in multidrug resistance in cancer is the high expression of ABC transporters proteins, including ABCG2." (PMID 23153066, 2012). "Yet, the influence of ABCG2 and ABCB1 on sorafenib exposure remains to be established in cancer patients." (PMID 22912756, 2012). "We investigated the expression of four markers that have previously been described for isolation of several types of human CSCs in human cancer cell lines: CD44, CD24, ABCG2, and EpCAM." (PMID 22328825, 2012). "Although these theories have yet to be confirmed by future work, what is clear is that ABCG2 is a key component of CSC-induced chemoresistance, making it a potential therapeutic target for smoking-induced cancers." (PMID 23144836, 2012). "EpCAM was co-expressed with all cancer stem cell markers (CD44, CD24, and ABCG2) in primary RB tumors." (PMID 22328825, 2012). "Most recently, it has been reported that PSCs increase the stem cell phenotype of cancer cells, as assessed by increased expression of stem cell markers such as nestin, ABCG2, and LIN28 in cancer cells upon co-culture with PSCs." (PMID 22973234, 2012). "Mechanisms involved in MDR include overexpression of multispecific ATP-dependent drug efflux pumps, such as P-gp (MDR1, ABCB1), MRP1, and BCRP (ABCG2), that reduce the concentration of the drug available for cancer cells." (PMID 22615870, 2012). "Consistent with the CSC concept, while survivin is expressed in all types of cancer, we showed that only a small subset of cancer cells express survivin, and its expression overlapped with several universal stem cell markers including CD133 and ABCG2." (PMID 23029106, 2012). "Flow cytometry was used to study the co-expression of EpCAM with putative cancer stem cell markers, such as CD44, CD24, and ABCG2, in RB primary tumors." (PMID 22328825, 2012). "The ABCG2 locus encoding a member of the ATP-binding cassette transporter proteins, also known as the Breast Cancer Resistance Protein (BCRP), has been intensively studied for its role in resistance to cancer chemotherapy." (PMID 23369448, 2012). "Two rotenoids isolated from B. diffusa, boeravinones G and H, have been found to potently inhibit the drug efflux activity of breast cancer resistance protein (BCRP/ABCG2), a multidrug transporter responsible for cancer cell resistance to chemotherapy." (PMID 21869896, 2011). "Using BCRP/ABCG2 as another predictor of the clinical response to gefitinib will help us to decide on the use and priority of anti-cancer therapies." (PMID 21731744, 2011). "On the other hand, induction of ABCG2 and HO-1 is considered as critical factors for PDT, and they can be readily induced by photo-oxidative stress to protect cancer cells." (PMID 21188243, 2010). "Thus, the inhibitor-induced ABCG2 degradation may be more common than we previously anticipated and further investigation of the dynamic inhibitors that induce ABCG2 degradation may provide a more effective way of sensitizing ABCG2-mediated MDR in cancer chemotherapy." (PMID 21151870, 2010). "Human ABCG2, a member of the ATP-binding cassette transporter superfamily, plays a key role in MDR and an important role in protecting cancer stem cells." (PMID 19479068, 2009). "PZ-39 is potentially a valuable probe for structure-function studies of ABCG2 and a lead compound for developing therapeutics targeting ABCG2-mediated MDR in combinational cancer chemotherapy." (PMID 19479068, 2009). "Vandetanib inhibited the transport function of ABCC1 and ABCG2 and sensitized MDR cancer cells to substrate drugs of the two transporters." (PMID 19390592, 2009).
cancer (continued). "We report that a single-step selection with low doses of anti-cancer agents, similar to concentrations reported in vivo, induces MDR that is mediated exclusively by ABCG2." (PMID 18382425, 2008). "Moreover, the second- and third-generation models shared co-targetable dysregulations in cancer stemness regulators (Hedgehog, Notch), anti-apoptotic protein BCL-2, and the drug efflux transporter ABCG2." (PMID 42087187, 2026). "Luteolin induces apoptosis in P-glycoprotein- and ABCG2-expressing MDR cancer cells without affecting the transport functions of these drug transporters." (PMID 40352931, 2025). "ABCG2 expression is notably elevated in the side population (SP) of stem-like cells, which exhibit enhanced drug resistance compared to non-stem-like cancer cells, highlighting its importance in maintaining the chemoresistant phenotype of CSCs101." (PMID 40830621, 2025). "In addition to ABCB1, efflux transporters ABCG2 and ABCC1 are also well known for their role in cancer chemoresistance." (PMID 40362377, 2025). "ABCG2-overexpressing cancer cell lines and their nonresistant parental counterparts were cultured as monolayers and as multicellular spheroids." (PMID 40584625, 2025). "In a second ABCG2-positive cancer model, we also showed that there was no combination effect of ABCG2-inhibition and paclitaxel or Gem." (PMID 40272619, 2025). "ABCG2, a member of the ABC superfamily, is a major contributor to drug resistance in cancer." (PMID 41154846, 2025). "Additionally, results for other drug sensitivity markers (ABCG2, ABCB1, BCL2; P < 0.00001) and cancer stem cells (CSCs) markers (ALDH1A1, PROM1; P < 0.01) were also presented." (PMID 40264043, 2025). "miR-7-5p/ABCC1/SLC7A5, miR-107/RAD51, miR-124-3p/ABCC4/SLC16A1/MGMT, miR-212-3p/ABCG2, miR-381-3p/GJA1 and miR-485-3p/SLC40A1 may modulate pathways that confer chemoresistance to cancer cells." (PMID 40061896, 2025). "A study on cancer stem-like traits revealed that, in MDA-MB-231 breast cancer cells, subpopulations with high CD147 surface expression show enhanced membrane localization of CD44, EGFR, MCT4, ABCB1, and ABCG2, highlighting their coordinated interactions." (PMID 41479915, 2025). "In the pan-cancer survival analysis, ABCG2 showed that, unlike in the liver, a low expression of ABCG2 in KIRC and KIPAN was associated with a poor prognosis." (PMID 40282409, 2025). "The breast cancer resistance protein (BCRP/ABCG2), a member of the ATP-binding cassette (ABC) transporter family, plays a pivotal role in mediating multidrug resistance by actively effluxing a broad range of chemotherapeutic agents out of cancer cells." (PMID 40649736, 2025). "Indeed, we showed that SHH-DAOY cells when grown as medullospheres in low adherence had increased expression of cancer stem cell markers, CD133 and ABCG2, when compared to the same cells grown in standard 2D culture." (PMID 40495204, 2025). "Previous studies have shown that ABCG2 and human clusters of differentiation 33 (CD133) markers are highly expressed in drug-resistant and highly tumorigenic cell lines, such as MDA-MB-231 and MCF-7, which resemble cancer stem cells (CSCs)." (PMID 38787133, 2024). "Finally, two genes that are widely overexpressed in drug-resistant cancers, the glutathione S-transferase Pi 1 (GSTP1) and ABCG2, a member of the ATP-binding cassette family, were also found in this cluster." (PMID 38999963, 2024). "Extracts of Scutellaria barbata inhibit the activation of the PI3K/Akt pathway, reducing the expression level of the ABC transporter ABCG2, suppressing the efflux function of ABC transporters, and increasing drug accumulation in cancer cells, thereby exhibiting anti-tumor activity." (PMID 39274982, 2024).
cancer (continued). "While investigating the mechanism by which ABCG2 enhances survival in stressful milieus, we have identified a physical and functional interaction between ABCG2 and SLC1A5, a member of the solute transporter superfamily and the primary transporter of glutamine in cancer cells." (PMID 38641063, 2024). "In conclusion, our study underscores that MTX-211 functions as a substrate for ABCG2, suggesting that this transporter may contribute to the resistance against MTX-211 in cancer patients." (PMID 38791198, 2024). "The results of the pan-cancer analysis demonstrated that the level of ABCG2 gene expression differed significantly between tumor and normal tissue in more than half of the cancer types (16 out of 23)." (PMID 39457707, 2024). "Their list did not include ABCG2, likely because this study did not include cancer patients, however this points to existence of other channels that can additionally assist in the excretion of CS." (PMID 38442133, 2024). "The observation that ABCG2 interacts with the amino acid transporter SLC1A5 to regulate glutamine metabolism suggests a new and previously unexplored role for ABCG2 in the regulation of cancer cell survival." (PMID 38641063, 2024). "Despite the complexity of the tumor microenvironment, which requires further confirmation including in vivo study, this work revealed a new approach of combining RN486 with conventional or innovative anticancer drugs for cancer patients diagnosed with overexpressed ABCB1 and ABCG2." (PMID 39081282, 2024). "ABC transporters, especially ABCG2, ABCB5, and ABCB1, regulate therapeutic resistance in cancer." (PMID 39309691, 2024). "Similarly, IGF2BP3 overexpression de-sensitized sorafenib and doxorubicin by enhancing cancer stem cell marker CD133 and drug efflux proteins such as ABCB1 and ABCG2 in human hepatocellular carcinoma." (PMID 38328550, 2024). "Cancer stem cells have been found to be multidrug-resistant (MDR) based on high expression of the multidrug transporter ATP-binding cassette super-family G member 2 (ABCG2) which is an efflux protein, also called the breast cancer resistance protein (BCRP)." (PMID 37696458, 2023). "In both the S1-MI-80 and H460-MX20 cancer cell lines, no notable alteration in the expression of ABCG2 was observed." (PMID 38004460, 2023). "Indeed, it is reported that vemurafenib is a substrate of P-glycoprotein and BCRP (breast cancer resistance protein, ABCG2); therefore, ABCB1 overexpression in the cancer cells can simply avoid intracellular accumulation and activity of vemurafenib." (PMID 37508582, 2023). "At present, no clinically approved inhibitors of ABCB1 or ABCG2 exist for combating multidrug-resistant cancers, primarily due to unexpected adverse drug reactions." (PMID 37762275, 2023). "First, differences in ABCG2 expression between cancers of various origins and comparable noncancerous tissue from healthy individuals were assessed via the Oncomine platform." (PMID 37445716, 2023). "First, we compared the effect of 2 μM HS-173 on cell cycle phase distribution in KB-3-1, KB-V1, S1, and S1-MI-80 cancer cell lines with or without the addition of a reference inhibitor of ABCB1 or ABCG2." (PMID 37048130, 2023). "Here we reported the effect of carborane-containing therapeutics—ABCG2 inhibitors that were effective in low dosage, non-toxic to cancer cells, and performed in synergy when combined with doxorubicin and cisplatin." (PMID 38004447, 2023). "In this study, we found that neither ABCB1 nor ABCG2 confers significant resistance to furmonertinib in cancer cells." (PMID 37762275, 2023). "Among the various mechanisms contributing to the MDR phenotype in cancer, a significant factor is the high expression of ATP-binding cassette (ABC) drug transporters, particularly ABCB1 (P-glycoprotein/MDR1) and ABCG2 (BCRP/MXR/ABCP)." (PMID 38004460, 2023).
cancer (continued). "More importantly, the efficacy of HS-173 in multidrug-resistant cancer cells could be recovered by inhibiting the drug-efflux function of ABCB1 and ABCG2." (PMID 37048130, 2023). "Overcoming ABCG2-mediated drug resistance using tyrosine kinase inhibitors may thus ultimately benefit the anti-cancer efficacy of transcriptional CDK inhibitors and other ABCG2 substrates in the clinic." (PMID 37147730, 2023). "ABCG2 (ATP-binding cassette subfamily G member 2, also known as the breast cancer resistance protein (BCRP)) mediates MDR by an increased drug efflux from the cancer cells." (PMID 36678870, 2023). "ABCG2 and MRP1 have been identified as the major molecules mediating the resistance to several drugs, including cisplatin, 5-fluorouracil and gemcitabine, in different types of cancer." (PMID 37489008, 2023). "Although ABCG2 role in the development of drug resistance in cancer cells is known, the regulatory mechanisms that enhance the expression of this protein in cancer cells and create a growth advantage have not yet been identified." (PMID 37166017, 2023). "Moreover, we discovered that furmonertinib effectively inhibits the drug efflux function of ABCB1 and ABCG2, leading to a substantial restoration of drug-induced apoptosis and reversal of MDR in cancer cells overexpressing these transporters." (PMID 37762275, 2023). "On the other hand, the total protein level of ABCG2 in ABCG2-overexpressing cancer cells lines was not significantly altered as a result of incubation with hydroxygenkwanin for 72 h." (PMID 36361555, 2022). "In the N-thy ori-3-1 cells there was a non-significant reduction in expression of ABCG2 whereas, for both cancer lines expression was significantly reduced when comparing BCPAP to control (p < 0.05) and SW1736 to control (p < 0.005)." (PMID 35118633, 2022). "Our data indicated that ensartinib is a substrate for P-gp, but not for ABCG2, and the intracellular concentration of ensartinib was significantly reduced by the activity of P-gp in human cancer cells." (PMID 35565470, 2022). "We found that hydroxygenkwanin is equally cytotoxic to both parental and multidrug-resistant cell lines, thus suggesting that it is not rapidly transported out of cancer cells by either ABCB1 or ABCG2." (PMID 36361555, 2022). "Specifically, BCRP1/ABCG2, an ABC transporter, has been shown to play a major role in development of the SP phenotype in stem and progenitor cells during murine hematopoiesis and spermatogenesis and in human cancer stem-like cells." (PMID 35334216, 2022). "In addition, a synergistic effect can be induced by co-administering pelitinib and various other anti-cancer drugs to advanced cancer patients that express high levels of LEPRE1 and ABCG2." (PMID 35190588, 2022). "At the same time, these results suggest that talazoparib might be a highly effective dual-activity MDR antagonist in cancer cells with ABCC1 and/or ABCG2 overexpression." (PMID 36430819, 2022). "Similarly, the decreased levels of SOX4, SOX9, Nanog,CD44, KLF4 and ABCG2 were observed from the harvested KYSE450 tumors related to miR-637 overexpression, indicating the inhibition of cancer cell stemness by miR-637." (PMID 36329557, 2022). "The influence of ABC pumps in anthracycline pharmacokinetics has been suggested in vitro and studies in other cancers, but a population pharmacokinetic study performed in AML failed to reproduce these findings with ABCB1 and ABCG2 polymorphisms." (PMID 35456712, 2022). "It is exciting that ZSTK474 induced the degradation of multidrug efflux pumps ABCB1 and ABCG2 so as not to be affected by the efflux effect of resistant cancer cells." (PMID 35918352, 2022). "The potential mechanism of the action responsible for this interaction might be inhibition of ABCG2/Abcg2 multidrug transporter, which is responsible for the transportation of MTX out of the cancer cells." (PMID 35743195, 2022).
cancer (continued). "Nilotinib, a second-generation of TKI, also inhibited the efflux function of ABCB1, ABCG2, and ABCC10 in cancer cells, thereby increasing the intracellular concentrations of the chemotherapeutic agents (e.g., PTX and doxorubicin) and potentiating their cytotoxic effects both in vitro and in vivo." (PMID 35327403, 2022). "RNA isolation from co-cultures has confirmed that the mRNA pattern of ABCB1 and ABCG2 does not differ significantly between the various cancer cell line containing aggregates either in all cell type containing or in epithelial cell specific (CK7) calculations." (PMID 34065402, 2021). "Three transporters have been extensively identified in TNBC comprising (i) multidrug-resistant protein-1 and -8 (MRP1 and 8), (ii) breast cancer resistance protein (ABCG2), and (iii) the P-glycoprotein (MDR1) pump which pumps a wide array of chemotherapeutics out of the cancer cells." (PMID 34376211, 2021). "However, proteins from other subfamilies, such as ABCB (ABCB1, glycoprotein-P or multidrug protein (MRP)) and ABCG (ABCG2, breast cancer resistance protein (BRCP)), also contribute to cancer irresponsiveness to chemotherapy." (PMID 34572840, 2021). "Next, knowing that TP-3654 selectively reverses ABCG2-mediated MDR by inhibiting the drug transport function of ABCG2, we examined the effect of TP-3654 on drug-induced apoptosis in ABCG2-overexpressing cancer cells." (PMID 34502348, 2021). "All indeno[1,2-b]indole derivatives are not transported by ABCG2, and even the partial inhibitors are able to fully chemosensitize cancer cells overexpressing ABCG2." (PMID 33469044, 2021). "We discovered that TP-3654 did not significantly affect the protein expression of ABCG2 in S1-M1-80 or H460-MX20 cancer cells." (PMID 34502348, 2021). "We found that the reduced intracellular accumulation of citarinostat in KB-V-1 and S1-M1-80 cancer cells was significantly restored by tariquidar and Ko143, signifying that the activity of ABCB1 and ABCG2 contributes greatly to the reduced efficacy of citarinostat in these cancer cells." (PMID 33807514, 2021). "CD44, ABCG2, Nanog, SOX2, and Oct4 were identified as important stem-cell transcription factors or markers involved in maintaining the CSC-like phenotypes in many kinds of cancer." (PMID 33596919, 2021). "The incubation of S1-M1-80 cancer cells with 5 μM of VKNG-2 for 72 h did not significantly alter the expression level of the ABCG2, PI3K p110β (B) and AKT (C) proteins compared to cells incubated with the vehicle." (PMID 33671108, 2021). "Furthermore, it has been reported that the activation of the PI3K/AKT pathway increases the expression of the ABCG2 protein, thereby increasing the likelihood of MDR in certain cancer cells." (PMID 33671108, 2021). "The levels of ABCG2, C-Myc, Bmi1, and Sox2 were repressed by the depletion of circNOLC1 in MDA-MB-231 and MDA-MB-468 cells, implying that the inhibition of circNOLC1 attenuates cancer stem cell properties." (PMID 34789263, 2021). "Overexpression of Pgp and/or some other drug transporting ABC proteins (e.g., ABCG2, MRP1) in cancer cells and cancer stem cells often renders the malignant tumors resistant to the different cytotoxic agents used in cancer chemotherapy, leading to the phenomenon of multidrug resistance (MDR)." (PMID 34959345, 2021). "While various mechanisms are responsible for resistance of cancer cells to cytotoxic drugs, overexpression of ABC efflux proteins (e.g., P-gp/ABCB1, BCRP/ABCG2 and MRP/ABCC1) on the tumor cell membrane play a significant role in the emergence of resistance to antineoplastic drugs." (PMID 33918289, 2021). "The side population of cancer cells, which excludes the fluorescent dye Hoechst 33342, expresses a high level of ABCG2 (BCRP) and displays chemoresistant phenotypes." (PMID 35155201, 2021).